CRP (C-reactive protein)
Diseases named in the same sentence as CRP in open-access papers (continued):
Sharing a sentence is not in itself a finding about the gene and the disease.
infection (continued). "Among them, CRP, an acute phase-responsive protein, can be extremely increased in case of infection or inflammation and is associated with criticality of the disease." (PMID 35693303, 2022). "Again, CRP ≥2 mg/L was associated with increased risk of all categories of death, but nominally higher IRRs were observed for infection death than cardiovascular or other death in all morbidities except “other neurological diseases”." (PMID 35535512, 2022). "The association of mean levels of P-SEP, IL-6, PCT and CRP with the risk of infection at T0 was strong for P-SEP (p < 0.001) and CRP (p = 0.003) and weak for PCT (p = 0.214) and IL-6 (p = 0.088)." (PMID 36699313, 2022). "To investigate this, we tested the diagnostic performance of PSP for patients suspected of an infection at the ED and compared it with that of C-reactive protein (CRP) and white blood cell count (WBC)." (PMID 35631080, 2022). "The association between CRP and presepsin increases the diagnostic accuracy of these biomarkers in terms of infection diagnosis in patients with LC." (PMID 36140479, 2022). "Although CRP initially works to restore the body after infection or injury, high circulating levels of CRP have been linked to adverse health outcomes." (PMID 35731783, 2022). "Increased serum level of C-reactive protein (CRP) is the biochemical indicator of such infection associated inflammation." (PMID 34867361, 2021). "CRP is a major acute-phase protein in dogs, mostly synthesized in the liver after tissue damage caused by infection, inflammation, or trauma." (PMID 34566333, 2021). "In order to reduce the risk infection, one should always exclude infection (in our case the patient’s C-reactive protein concentration before the procedure was 2 mg L−1)." (PMID 33821220, 2021). "In our cohort, a higher CRP (indicating a more severe infection) was also associated with a worse AFS." (PMID 33996886, 2021). "After excluding participants with suspected infection, defined as having CRP > 10 mg/L at baseline, the evidence for an association remained only in the unadjusted, but not in the adjusted, analyses." (PMID 34050185, 2021). "When assessing the diagnostic accuracy to identify confirmed and suspected infection, CRP again performed best with an AUC of 0.72 (95% CI 0.61–0.84)." (PMID 35155322, 2021). "In multivariate analysis, the factors associated with the severity of the infection were CRP (OR: 1.007, CI 95%: (1.005–1.010), p < 0.001), NLR at H-24 (OR: 1.117, CI 95%: (1.060–1.176, p < 0.001), and ΔNLR (OR: 1.877, CI 95%: (1.160–3.036); p: 0.01)." (PMID 34207918, 2021). "Patients with PJI caused by a low-virulent microorganism (median CRP: 17.6 mg/L) obtained lower CRP levels compared with infections caused by high-virulent microorganisms (median CRP: 49.2 mg/L; p = 0.044)." (PMID 33247312, 2021). "Additional studies are needed for the monitoring of CRP levels secondary to flares or infections in MAS associated with SLE patients." (PMID 34804679, 2021). "For infectious diseases, CRP levels are expected to be elevated after infection, which would entail a kind of reverse causality with respect to how our regression models are specified." (PMID 34733313, 2021). "Within a few hours of an infection or other stressor, cytokines secreted by immune cells will enter the bloodstream and cause the liver to secrete CRP." (PMID 34485323, 2021). "After adjusting for age, B.1.1.7 variant infection was a risk factor for elevated CRP (P = 0·045), SAA (P = 0·011), CK (P = 0·034), and CD4+ T (P = 0.029) and for the presence of GGO (P = 0.005)." (PMID 34346755, 2021). "Modest evidence of association of the infection biomarkers CRP and AGP with the composition of gut microbiota was observed at baseline, but not at endpoint." (PMID 33634319, 2021). "The levels of PCT and CRP have higher differential diagnostic value than that of WBC in infection, and the combined examination of the three is more valuable in clinic." (PMID 34836530, 2021).
infection (continued). "Correlation of albumin levels and severity of the infection is presented through the specific CRP/albumin ratio, already marked as an independent risk factor for severe COVID-19 infection." (PMID 33968298, 2021). "The diagnostic accuracy to identify confirmed infection was best for CRP with an AUC of 0.79 (95% CI 0.66–0.92), and it was worst for PCT with an AUC of 0.57 (95% CI 0.35–0.80) and." (PMID 35155322, 2021). "WBC counts are affected by factors other than inflammation and infection, such as trauma, acute blood loss, and medications, making this a less reliable marker than CRP and PCT levels for predicting CRPF." (PMID 33784995, 2021). "Serum levels of CRP, a marker of systemic inflammation, increase from the early stages of infection, and recent data proved that CRP level is positively associated with CT severity of COVID-19 infection (p < 0.01)." (PMID 34685421, 2021). "Several studies have assessed the association between infection, represented by elevated levels of CRP, and PK variations of voriconazole." (PMID 34867341, 2021). "Serum levels of CRP are usually used to track and monitor the inflammatory response caused by infection due its short half-life of 19 h." (PMID 33967773, 2021). "Under normal conditions, CRP content is very low, but it rises sharply when there is an acute inflammatory response caused by infection." (PMID 34745285, 2021). "Elevated levels of circulating CRP are associated with response to infection, risk for a number of complex common diseases, and psychosocial stress." (PMID 34733313, 2021). "C reactive protein (CRP) was considered as a systemic inflammatory marker associated with the severity of the infection." (PMID 34944747, 2021). "CRP is an acute phase protein formed by hepatocytes caused by leukocyte-derived cytokines induced by infection, inflammation, or tissue damage." (PMID 33897907, 2021). "CRP is one of the commonest biomarkers that should be analyzed to diagnose the extent of infection-associated inflammation." (PMID 34829902, 2021). "For SLR, CRP (p = 0.001) and a cardiovascular focus of infection (p = 0.020) were independently and positively associated with SLR, while age (p = 0.002) and glucose level before FDG-PET/CT (p = 0.016) were independently and negatively associated with SLR." (PMID 33106925, 2021). "CRP associated with infection and injury in the organism had a significant effect on serum MMP9 levels." (PMID 34938784, 2021). "Increased levels of CRP generally are reflective of underlying inflammation, such as that resulting from trauma or infection." (PMID 33791178, 2021). "High CRP levels have been correlated with increased risk of infection and overall mortality in HLH, suggested to be indices of disease severity." (PMID 35004761, 2021). "This study aimed to determine the serum protein electrophoresis patterns (SPEPs) and C-reactive protein (CRP) levels associated with Ehrlichia canis,Babesia canis, or Hepatozoon canis single infections." (PMID 34566333, 2021). "A statistically significant difference was shown between these groups with lower CRP levels in patients with an infection caused by a low-virulence organism (p = 0.044)." (PMID 33247312, 2021). "This is because CRP levels can often correlate with infection severity, with a small associated lag time." (PMID 34207560, 2021). "In conclusion, while CRP performed best to diagnose infection for children on ECMO, its diagnostic accuracy was only moderate." (PMID 35155322, 2021). "Meta-analyses of observational studies and MR studies examining associations between CRP and health outcomes were identified, excluding studies on the diagnostic value of CRP for infections." (PMID 32978716, 2021). "Factors associated with infection severity were C-reactive protein level (OR: 1.007, CI 95%: [1.005–1.010], p < 0.001), NLR at H-24 (OR: 1.117, CI 95%: [1.060–1.176], p < 0.001), and ΔNLR (OR: 1.877, CI 95%: [1.160–3.036], p: 0.01)." (PMID 34207918, 2021).
infection (continued). "This study aimed to investigate the SPEPs and CRP concentrations associated with single infections of E. canis, B. canis, and H. canis." (PMID 34566333, 2021). "This underlines the importance of fast detection of unusual CRP behavior and checking signs of infection within this constellation." (PMID 33266181, 2020). "It is likely that most bacteria detected in the current study caused a self-limiting infection, while previous CRP evaluations included more severe and hospitalised patients with bacteraemia detected by blood culture." (PMID 32437937, 2020). "GlycA is shown to be a biomarker for chronic inflammation, neutrophil activity and risk of future severe infection, even superior compared with CRP." (PMID 32677943, 2020). "Regardless, some reports have shown that PCT is more specific and has better diagnostic accuracy than CRP for infection in SLE15,34,35." (PMID 33199770, 2020). "They concluded that the CRP level is a better diagnostic marker for the early detection of postoperative infections than ESR." (PMID 35236472, 2020). "Increased concentrations of CRP have been found in natural infection with B. canis caused by marked acute phase response." (PMID 33144631, 2020). "Of the analyzed inflammatory markers, only peak CRP beyond first 48 postoperative hours was found to be significantly associated with infections." (PMID 32127631, 2020). "We also observed an association between depleted vitamin C status and elevated C-reactive protein, a marker of infection severity." (PMID 32599718, 2020). "CRP can also measure the incidents of implant-associated infections in orthopaedic surgery with iodine-supported titanium implants." (PMID 32028745, 2020). "C-reactive protein was already reported to be associated with infection in patients with severe DKA." (PMID 32430795, 2020). "Experiments employing CRP-deficient mice are in progress to confirm the participation of endogenous murine CRP in E-CRP-1-mediated protection against late-stage infection." (PMID 33117400, 2020). "We found that a history of preterm birth, hospitalization in the last six months, intra-abdominal source of infection, organ failure, low serum albumin, and high levels of C-reactive protein and lactate, were independent risk factors for 90-day mortality." (PMID 33267829, 2020). "The correlation with markers of infection and inflammation has been confirmed by others, with lower plasma glutamine levels found to be associated with lower albumin levels, higher CRP levels, and higher circulating IL-1β and IL-6 levels." (PMID 32028696, 2020). "As an internal control, it was validated that all participants presented CRP levels below the limit associated with active inflammation/infection (10 mg/L)." (PMID 32983153, 2020). "Several biological parameters reflecting the severity of the infection were also associated with both primary outcome and death on day 7, such as CRP, creatine phosphokinase (CPK) and lymphopaenia." (PMID 32472191, 2020). "C-reactive protein (CRP), a potent acute-phase reactant that increases rapidly in response to inflammation, tissue damage or infections, is also considered an indicator of the risk of cardiovascular diseases and neurological disorders." (PMID 32992442, 2020). "C-reactive protein (CRP) is an acute-phase protein and the concentration in blood increases in response to inflammation caused by infection, tissue injury or other inflammatory processes." (PMID 33174788, 2020). "Of those representing CRP changes, only peak CRP concentration beyond first 48 postoperative hours was significantly associated with infections (p = 0.038)." (PMID 32127631, 2020). "Intakes of dietary ω-3 fatty acids are associated with reduced lymphocyte proliferation and Th1 cell development, lower circulating levels of leptin, C-reactive protein and other pro-inflammatory cytokines, as well as a lower risk of infection." (PMID 32028957, 2020).
infection (continued). "Hospitalization in the last 6 months, intra-abdominal source of infection, presence of organ failure, and altered levels of blood biomarkers, including C-reactive protein, albumin, and lactate were significant risk factors for 90-day mortality." (PMID 33267829, 2020). "CRP has marginally superior diagnostic accuracy for infections, and is equivalent for autoimmune conditions and cancers, so should generally be the first-line test." (PMID 31208975, 2019). "Child’s BMI, siblings, bacterial airway colonization, current infection, CRP-genetic risk score and season were associated with higher hs-CRP at age 6 mo (all p < 0.05)." (PMID 30816254, 2019). "PCT is superior to CRP in diagnosing infection, and it is significantly less susceptible to tumour factors than CRP." (PMID 30976022, 2019). "There were significant associations between CRP levels and infection (p < 0.001) whereas 61.3% of patients with infection had moderate-severe inflammation." (PMID 31443557, 2019). "“Convalescence” suggests that a person is recovering from illness, but asymptomatic infections can also cause elevated CRP or AGP concentrations." (PMID 30781529, 2019). "Around the same time, Garges and Adhya used crp-carrying phages for infection and growth in a mutator E. coli strain for CRP mutant generation." (PMID 31303977, 2019). "Further investigation with a larger sample set is necessary to understand the association between CRP levels and low parasite density infections." (PMID 30404944, 2019). "With other serologic markers including CRP, prothrombin time, aPTT, creatinine, and albumin associated with infection, DNI significantly predicted death within 30 days after abdominal surgery." (PMID 30985959, 2019). "A cluster randomised controlled trial from Belgium concluded that CRP testing should be targeted at children at risk of severe infections." (PMID 30554748, 2019). "A cluster randomised trial in Belgium concluded that CRP testing in primary care should be targeted at children at high risk of severe infection after clinical assessment." (PMID 30554748, 2019). "It is predicted to encode a secreted cysteine‐rich peptide (CRP), many of which have been reported to play roles in pollination and defence against pathogen infection." (PMID 31001872, 2019). "In this paper, we use C-reactive protein (CRP), a biomarker associated with infection and stress, alongside information relating to housing details, demographic characteristics and health behaviours taken from the UK Household Longitudinal Study." (PMID 30642891, 2019). "The goal of this study is to analize which antepartal, peripartal and postpartal factors are associated with an increase of CRP on the second day postpartum and which factors, together with CRP, predict infections in the postpartum." (PMID 32082531, 2019). "P-SEP is reported to be a novel infection marker indicating a higher diagnostic capability than CRP and also reflecting severity." (PMID 31139474, 2019). "CRP is often used as an inflammatory biomarker that is indicative of malaria parasitemia and other infections associated with febrile illness." (PMID 30404944, 2019). "In HSCT patients, diagnostic values of PCT and CRP for detecting infections are controversial, and previous studies have focused on different target populations." (PMID 31821331, 2019). "In infection patients, their CRP level often is susceptible to multiple factors, such as cancer, anti-inflammatory medication and perioperative period, and sometimes it is difficult to judge when the detection results fluctuate greatly." (PMID 30976022, 2019). "Our results show that CRP was a poor marker of infection in patients with severe AKI whereas suPAR had a stronger association with the development of an infection." (PMID 30071826, 2018). "Addition of each confounder separately to the unadjusted model suggested that BMI, maternal occupation and atopic status most confound the association between very high infection burden and CRP." (PMID 29198208, 2018).
infection (continued). "Our study is one of only a very few to assess the diagnostic accuracy of CRP and procalcitonin for the three commonest infections in HIV-infected inpatients." (PMID 30107791, 2018). "The risk factors that promote this early elevation of some LTs are events such as surgery-, cancer- and infection-associated oxidative stress, as well as inflammatory response (CRP and leukocytes) and days on PN treatment." (PMID 30474548, 2018). "Our study showed that suPAR concentrations had better diagnostic and predictive value than CRP to detect infections in critically ill patients with severe AKI." (PMID 30071826, 2018). "The association of widely used C-reactive protein (CRP) with severe AKI in PUUV infection is less clear." (PMID 30517161, 2018). "One is that the use of CRP overestimates bacteria as the cause of the infection, and secondly, and more importantly, that the measurement of HNL in whole blood after activation specifically reflects the body’s response to a bacterial infection." (PMID 29473432, 2018). "This study evaluated the propensity of AF hs-CRP in predicting CS-associated infection and inflammation." (PMID 29686267, 2018). "C-reactive protein(CRP) is a pentameric protein found in blood plasma associated with inflammation, infection, and injury." (PMID 29351749, 2018). "We evaluated the diagnostic accuracy of CRP and procalcitonin, compared with composite reference standards, to discriminate between the three target infections in adult HIV-infected inpatients in two district level hospitals in Cape Town, South Africa." (PMID 30107791, 2018). "CRP is an acute phase reactant that is produced in response to inflammation caused by infection or tissue injury." (PMID 29311572, 2018). "First, higher infection burden was associated with higher levels of IL-6 and CRP, but this association was explained by body mass, atopic disorder and socio-economic status." (PMID 29198208, 2018). "We evaluated the diagnostic accuracy of CRP and procalcitonin for differentiating between the three major infections affecting HIV-infected adult inpatients." (PMID 30107791, 2018). "Previous studies have shown associations between a raised neonatal CRP and a number of neonatal condition including infection, perinatal asphyxia and meconium aspiration, and so an association with maternal and newborn infection cannot be assumed." (PMID 28780500, 2018). "We have examined prospective associations between exposure to common and serious infections during childhood and subsequent serum levels of IL-6, CRP and general intelligence." (PMID 29198208, 2018). "The strong positive association of CP and CRP on day 3 suggests that CP is related to the severity of infection." (PMID 28358335, 2017). "In our previous Bio-X study, CRP was known to the adjudicator and used to classify patients as having a bacterial or viral cause of infection." (PMID 28468981, 2017). "CRP is an acute phase reactant made by the liver and released into blood stream within few hours after tissue injury, the start of an infection, or other cause of inflammation." (PMID 28798859, 2017). "In fact, CRP levels at the day of discharge >20 mg/l (normal ≤5 mg/l) did associate strongly with the failure of infection clearance." (PMID 28592300, 2017). "Of 20 patients with plantar ulcers, 4 patients had elevated CRP levels, 1 patient had a clinically evident infection, and 3 patients had erythematous skin of uncertain cause surrounding the ulcers." (PMID 28866982, 2017). "It was therefore of considerable interest that the diagnostic performance of HNL became superior to that of CRP when these biomarkers were evaluated in the cohort in which the likely cause of the infection was verified by objective microbiological testing." (PMID 28468981, 2017). "The diagnostic utility of IL-6 is inferior to CRP and the finding conflicts with previous conclusions drawn from periprosthetic infections." (PMID 29130050, 2017).